CXCL12 (C-X-C motif chemokine ligand 12)
Diseases named in the same sentence as CXCL12 in open-access papers (continued):
Sharing a sentence is not in itself a finding about the gene and the disease.
tumor (continued). "It is an antagonist of chemokine (C-X-C motif) ligand 12 (CXCL-12), which inhibits tumor cell proliferation, new blood vessel formation, and metastasis." (PMID 34095130, 2021). "It was demonstrated that the combination of CXCL12 with CXCR4 and CXCR7 on tumor cells leads to antiapoptotic signals upregulated by Bcl‐2 and survivin, and affects the progression of gastrointestinal tumors." (PMID 33979042, 2021). "In bone metastases, CXCL12 and CXCR4 can be produced or expressed by a broad panel of cell types such as osteoblasts, osteocytes, CAFs, neutrophils, tumor cells, and adipocytes." (PMID 34064859, 2021). "Two of these subtypes (CAF subtype 1 and subtype 4) produce TGF-β and CXCL12 and activate the NOTCH signaling pathway to promote tumor cell invasion." (PMID 34241649, 2021). "In MM, it has been reported that both tumor cells and BM mesenchymal stromal cells produce chemokines such as CXCL12, CCL2, CCL3, and CCL14 that promote macrophage migration to the tumor niche and polarize macrophages towards an M2-like phenotype in vitro." (PMID 33435306, 2021). "The immunomodulatory factors SerpinE1, TGFβ1, CXCL1 and CXCL12 act directly on immune cells to induce a wound-healing phenotype that contributes to angiogenesis, epithelial-to-mesenchymal transition (EMT), tumour growth and metastasis." (PMID 34885111, 2021). "In addition, cancer cell migration involving the CXCL12→CXCR4 axis may be caused by other cells—for example, CAFs in gastric cancer, where chronic hypoxia increases the expression of CXCL12 and thus acts on tumor cells with a hypoxia-enhanced expression of CXCR4." (PMID 33467722, 2021). "In this review, we will provide the latest evidence about the interactions between CSC niche-derived CXCL12 and its receptors—CXCR4 and CXCR7—present on CSC populations across different tumor entities." (PMID 33530455, 2021). "IL-4, the predominant cytokine produced by TFH, was shown to trigger production of CXCL12 by FRC-like stromal cells, thus supporting FL tumor cell activation and survival." (PMID 33842331, 2021). "CXCL12/CXCR4 axis promotes migration and survival of MDSCs in osteosarcoma inhibiting cytotoxic T cell (CTL) expansion and thus controlling tumor growth." (PMID 33937018, 2021). "ASC deletion of CXCL12 gene in the Pdgfr + lineages suppressed tumor growth and EMT, indicating stroma as the key source of CXCL12." (PMID 33753872, 2021). "As one of the chemokines, CXCL12 and vascular endothelial growth factor (VEGF) have a synergistic effect on tumor angiogenesis." (PMID 34930323, 2021). "By preventing CXCL12/CXCR4 crosstalk, exposure to plerixafor resulted in reduced ERK1/2 signaling and consequently, decreased proliferation and invasion of disseminated tumor cells." (PMID 34831167, 2021). "For instance, CXCL10, CXCL12, CCL1, CCL19 and CCL21 produced by LECs can be sensed by tumor cells expressing cognate receptors and stimulate their chemoattraction towards lymphatic vessels." (PMID 33808959, 2021). "Adipocytokines CXCL12, ANGPTL2, and ANGPTL4 increase vascular permeability and act as a chemoattractant for tumor cells." (PMID 34212564, 2021). "It has been shown that tumor-derived angiopoietin-like protein 2 increases CXCR4 expression on tumor cells, thus increasing their responsiveness to CXCL12." (PMID 34064859, 2021). "CXCL12, also known as stromal cell-derived factor-1α, binds to its receptor CXCR4 and activates the CXCR4/CXCL12 axis; this leads to tumor proliferation, vascularization, and metastasis." (PMID 34885013, 2021). "In a preclinical study using an ovarian cancer model, dual blockade of the CXCL12/CXCR4 and PD-1-PD-L1 signaling cascades effectively reduces tumor burden and prolongs survival in tumor-bearing mice." (PMID 34771482, 2021). "The initial step of premetastatic niche formation in specific organ sites is mediated by tumor‐derived soluble factors such as TNF‐α, TGF‐β, CXCL12, placental growth factor and VEGF‐A49 as well as by tumor‐derived exosomes." (PMID 32761606, 2021).
tumor (continued). "PC-derived chemokine CXCL12 (SDF-1) can trigger the EGF/CSF-1 paracrine invasion loop to mediate the co-migration of TAM and tumor cells, after binding to its receptor CXCR4 on both TAMs and tumor cells (process ➁)." (PMID 34179005, 2021). "The M-MDSC is attracted to tumor sites by CCL2, CCL5, and CSF1 and PMN-MDSC was attracted by CXCL1, CXCL5, CXCL6, CXCL8, and CXCL12." (PMID 34858479, 2021). "An active CXCL12/CXCR4 pathway is considered a feature of aggressive tumors as it positively correlates with tumor size, grading, tumor recurrence, poor prognosis and patient survival." (PMID 33937018, 2021). "CXCR4 expression promotes breast cancer cell migration towards sites of potential metastasis that actively secrete CXCL12, the ligand of CXCR4, whose production is increased during tumor-promoting processes, such as angiogenesis and inflammation." (PMID 34830776, 2021). "Studies have found that blocking CXCL12 can activate the MAPK/PI3K/AP-1 signaling pathway in colon cancer cells, thereby blocking the growth of tumor cells." (PMID 34683963, 2021). "Xenografted tumours were excised for HE staining at 7th week, and the results manifested that the presence of PNI in CXCL12 group, saline group, AMD3100 group was 85.7% (6/7), 16.7% (1/6) and 0 (0/7), respectively." (PMID 34170080, 2021). "CXCL12 and CXCR7 were significantly altered in LNCaP xenograft tumor as compared to LNCaP cultured cells." (PMID 33808801, 2021). "Here, we reported that MK3 expression was positively correlated with the majority of chemokines and chemokine receptors, such as CCL, CXCL12, CCR, CXCR2, CXCR4, and CX3CR1, which play pro-tumor roles." (PMID 34938665, 2021). "In the TME, tumor cells recruit immature DCs from the peripheral blood by releasing multiple cytokines (e.g., VEGF, β-defensin, CXCL12, HGF, and CXCL8), which lack the ability to inhibit tumor angiogenesis." (PMID 34294146, 2021). "CAF can produce tumor-promoting cytokines such as CXCL12, IL-6, HIF1a, and TGF-b2, and monocytic MDSCs can promote tumor epithelial to mesenchymal transition (EMT)." (PMID 34831357, 2021). "Activated JNK increased the secretion of epidermal growth factor (EGF) or stromal cell-derived factor 1 (SDF-1/CXCL12), thereby increasing invasion of tumor cells and metastasis." (PMID 34207247, 2021). "While the Cxcl12 trap induced IFN-γ+ T cell infiltration, the Pdl1 trap enabled these T cells to kill the tumor cells." (PMID 33530455, 2021). "Tumour cells recognize secretary molecules i.e. CCL5 and CXCL12 released from stem cells and osteocytes." (PMID 34975909, 2021). "Recent studies have shown that CXCL12 is produced by stromal cells, secreted in the TME, and binds to CXCR4 on the surface of tumor cells, which is crucial for tumor metastasis and poor prognosis 5-7." (PMID 33854601, 2021). "The tumor cells secrete both immune-suppressive chemokines, such as IL8, GM-CSF, CCL-5,2,17 and CXCL12,17, and pro-inflammatory chemokines, such as CXCL9 and CXCL10." (PMID 34834282, 2021). "The increased expression of six CXC chemokines (CXCL4, CXCL9, CXCL10, CXCL11, CXCL12, and CXCL13) was related to tumor progression." (PMID 33767987, 2021). "The CXCL12/CXCR4 axis can activate the MEK/ERK, PI3K/AKT, and Wnt/β-catenin pathways to promote EMT, thereby promoting tumor invasion and metastasis." (PMID 34447750, 2021). "Treatment with this formulation trapped CXCL12 and altered the immune landscape of orthotopic KPC allografts, most notably through the induction of a pronounced CD8+ T cell infiltrate that primed tumours for checkpoint inhibition with a co-delivered PDL1 trap." (PMID 34944794, 2021). "In a tumor cell, chronic hypoxia increases the expression of VEGF and in some types of tumor cells it increases the expression of CXCL12." (PMID 33467722, 2021).
tumor (continued). "MSCs promptly migrate into tumor sites in response to chemokines, such as CCL2, CCL5, CXCL12, and CXCL16, and are expanded by cytokines, such as TGFβ, VEGF, FGF, and IGF, all of which are released from the tumor milieu." (PMID 33535613, 2021). "Similar to ROS induced senescent tumor cells, CSF1 and CSF1/CXCL12 overexpressing cells induced the upregulation of CD206 and showed an increased expression of the mRNAs associated with M2 macrophages." (PMID 33643790, 2021). "Blockade of the CXCL12/CXCR4 axis within the TME, promotes tumor cell apoptosis and enhances other anticancer therapies." (PMID 33980266, 2021). "Genetic perturbation of the CXCL12 gradient not only markedly attenuated tumour invasion, but also abrogated anoikis resistance, highlighting the significance of SASP in mediating tumour invasion and potential metastasis." (PMID 32981205, 2021). "The chemokine CXCL12 and its cognate receptor CXCR4, a transcriptional target of FOXC1 was shown to play central roles in cancer proliferation, angiogenesis, invasion, tumor microenvironment, as well as drug resistance induced by chemotherapy." (PMID 34540690, 2021). "The CSC niche components reviewed above play a crucial role in the regulation of the CXCL12/CXCR4 axis, interacting with each other and with the CSC population to sustain the tumor." (PMID 33530455, 2021). "The BM niche produce multiple factors like Annexin A2, TGF-β, CXCL12 and IGF (insulin-like growth factors), which allows tumour cells to remain in the dormant stage." (PMID 34975909, 2021). "Results revealed that CXCL12 was significantly positively correlated with the TIDE score, suggesting a substantial role for CXCL12 in T cell depletion in the tumor immune response." (PMID 34801033, 2021). "For instance, CAFs secrete growth factors such as CXCL12, HGF, EGF, IGF, IL‐6, IL‐8, IL‐11 and CCL5, which facilitate tumour growth." (PMID 33943003, 2021). "Our data show high expression of ligand in many tumor clusters, including high CXCL12 in Tr11, CXCL2 in Tr3, and CXCL16 in Tr10 with high CXCR4 receptor expression in tumor endothelial cells supporting prior reports." (PMID 34497364, 2021). "Key players in tumor progression, metastasis and survival are the receptor CXCR4 and its ligand CXCL12." (PMID 35111484, 2021). "In our paper, we also demonstrated that both the primary tumor H295R cell line and the metastatic MUC-1 cells produce CXCL12 and express its receptors." (PMID 34834449, 2021). "TAMs are mainly recruited from the periphery by chemokines released from tumor tissues, including CCL2, CCL3, CCL4, CCL5 and CXCL12." (PMID 34925375, 2021). "Macrophages are attracted to tumor sites expressing chemotactic factors such as CCL7, CCL8 and CXCL12." (PMID 34001208, 2021). "Recent preclinical studies have shown that DPP-4i can increase viability and proliferation of tumor cells, and accelerates EMT through the CXCL12/CXCR4/mTOR axis both in vitro and in vivo." (PMID 36860286, 2021). "Irradiated CAFs were found to excrete increased levels of CXCL12/SDF-1, ultimately promoting cancer cell migration, invasion and epithelial-mesenchymal transition, aiding in the overall tumor progression." (PMID 34663337, 2021). "These include blocking recruitment of TAM into the tumor by targeting chemokines such as CCL2 and CXCL12, which resulted in a reduction in tumor size." (PMID 34795675, 2021). "It has been suggested that disseminated tumor cells can use the same physiological mechanisms as those used by hematopoietic stem cells (HSCs) homing to bone, involving primarily the CXCR4/CXCL12 axis." (PMID 33671469, 2021). "Tao and his colleagues reported that effector B cells directly killed tumor cells via the Fas/FasL and CXCR4/CXCL12 pathways, and the killing activities can be improved by IL-2 and inhibited by IL-10." (PMID 34118931, 2021).
tumor (continued). "Taken together, our results confirm the central role of HIF-1α in the interactions between the tumor microenvironment and CLL cells, also elucidating the interplay with the CXCL12/CXCR4 axis." (PMID 34207596, 2021). "For both GBM and glioma, CXCL12 functions under hypoxic conditions in the CSC niche through an autocrine positive feedback loop that promotes cell survival, tumor progression, and cell proliferation, which can be inhibited by blocking CXCR4." (PMID 33530455, 2021). "Mechanistically, we found that cabozantinib treatment induced expression of neutrophil-related chemokines (CCL11 and CXCL12) and T cell-related chemokines (CCL8 and CX3CL1) in the tumor microenvironment." (PMID 33954115, 2021). "CXC-chemokine ligand 12 (CXCL12) is another immune-modulating factor that is expressed by FAP+ CAF cells and is responsible for tumor cell survival and T cell compartmentalization within the TME in a lung cancer mouse model." (PMID 33806802, 2021). "In the process of homing, tumor cells overexpressing CXCR4 or CXCR7 have higher potential to survive the circulation stage, guarded by CXCL12 secreted by bone stromal cells." (PMID 34830862, 2021). "MAFs activated by TGF-β1 increase the secretion of stromal cell-derived factor-1 (SDF-1, also known as C-X-C motif ligand 12, CXCL12), which binds to CXCR4 of tumor cells and promotes their TGF-β1 production in turn." (PMID 34112258, 2021). "It stimulates Tregs and MDSCs in tumor tissues via the production of TGF-β, VEGF and the chemokine C-X-C motif chemokine 12 (CXCL12)." (PMID 34359568, 2021). "By scavenging its chemokine ligands CXCL12 and CXCL11, ACKR3 exerts important functions in embryonic development, in the regulation of leukocyte and tumor cell migration across blood vessels and in B cell immunity/activation in germinal centers." (PMID 33857173, 2021). "While CXCR4 and CXCL12 were homogeneously expressed within tumor cells, ACKR3 was mainly identified in tumor endothelial cells but CXCL11 in pericytes." (PMID 32456359, 2020). "Ovarian cancer-derived TGF-β is involved in stimulating the production of various tumor-promoting factors including IL-6, CXCL12, and VEGF-A in the metastatic tumor microenvironment." (PMID 32546182, 2020). "CSCs recruit endothelial cells (ECs) to the tumor niche and induce angiogenesis by secreting HIF-1, VEGF and SDF-1/CXCL12." (PMID 33059744, 2020). "On the other side, tumor-released VEGFA, semaphorin 3A and CXCL12 recruit TAMs in pre metastatic niches, where they suppress the cytotoxic activity of CD8+ T cells and promote recruitment of Treg cells." (PMID 32397392, 2020). "CAFs together with endothelial cells generate local CXCL12 gradients to attract CXCR4+ progenitor cells such as endothelial progenitor cells, enhancing tumor angiogenesis." (PMID 33096815, 2020). "Conclusion, our clinical and experimental evidence strongly support that miR-204-5p act as a tumor suppressor in GC by targeting CXCR4 and CXCL12, thus regulating invasion and migration." (PMID 32231725, 2020). "The levels of eight hub genes expression (FN1, CCND1, CDH2, CXCL12, MET, IRS1, DCN and FMOD) in PTC and para-cancerous non-tumor tissues were detected by qRT-PCR." (PMID 32714651, 2020). "For example, the cytokine CXCL-12 is secreted by CAFs, while its receptor CXCR-4 is found mainly on tumor cells." (PMID 33585565, 2020). "Previous work had focused on the role of CXCL12 and its receptor CXCR4 in tumor development and how they affected overall prognosis of cancer patients." (PMID 33129326, 2020). "In a previous work, we reported the NFkB-induced expression of CXCR7 concomitant to the perturbation of the CXCR4/CXCL12 and VCAM-1/VLA-4 integrin axes, consistent with experimental evidence of its involvement in immune cell recruitment and tumor metastasis." (PMID 33062419, 2020).
tumor (continued). "CXCL12 binds to the receptors C-X-C Motif Chemokine Receptor 4 (CXCR4) and C-X-C Motif Chemokine Receptor 4 (CXCR7) and thus regulates tumor growth and tumor metastasis." (PMID 32498358, 2020). "There is an influx of CD11b+ myeloid cells following tumor irradiation, and increased tumor hypoxia increases HIF-1 levels and subsequently upregulates stromal cell-derived factor 1 (SDF1, also known as CXCL12) to initiate vasculogenesis." (PMID 33050580, 2020). "The CXCL12/CXCR4/CXCR7 axis plays key roles in many physiological and pathological processes, including embryogenesis, wound healing, angiogenesis, tumor development, as well as recruiting suppressive immune cells." (PMID 32381016, 2020). "Secretion of CXCL12/SDF1 and TGF-β by CAFs promotes tumorigenesis, and TGF-β increases HSF1 levels in tumor cells." (PMID 32331382, 2020). "Mounting evidences supported that the CXCL12/ CXCR4 / CXCR7 axis was related to multiple types of solid tumors and tumor cells." (PMID 33129326, 2020). "Monocytes are recruited from the circulation and differentiate into macrophages within the TME where stromal and tumor cells provide chemokines and growth factors mainly CCL2, CSF1, CCL18, CCL20, CXCL12, and VEGF-A." (PMID 31256327, 2020). "Circulating monocytes are recruited by several tumor-derived chemo-attractants as CCL2 (MCP-1), CCL3 (MIP-1), CXCL12 (SDF-1), and CSF-1 at tumor sites where they differentiate into TAMs and facilitate tumor progression." (PMID 33374253, 2020). "CXCL12 (stromal cell-derived factor 1) binds to CXCR4 and forms various downstream signaling pathways, resulting in multiple responses necessary for tumor growth and development, including chemotaxis and gene transcription." (PMID 33569348, 2020). "Along with its ligand CXCL12, CXCR4 controls the transduction of different downstream signaling pathways that are profoundly involved in tumor cell survival, proliferation, and migration." (PMID 33363463, 2020). "We aimed to explore the tumor expression of HGF, c-MET, CXCL12, and CXCR4 and their correlation with patient overall survival (OS)." (PMID 32188473, 2020). "Mechanistically, CXCL12 acts on endothelial cells through its receptor chemokine (C-X-C motif) receptor 4 (CXCR4) and promotes trans-endothelial migration of tumor cells." (PMID 33123472, 2020). "For example, CFA secretion of transforming growth factor-β (TGF-β) potentiates CXCR4 stimulation of AKT signaling in human prostate epithelial cells, which indicates that synergism between TGF-β, CXCL12, and CXCR4 in tumor stroma contributes to carcinogenesis." (PMID 33363463, 2020). "CXCL12 and its receptor, CXCR4, play pivotal roles in tumor development, progression, angiogenesis, and metastasis in various types of cancers." (PMID 32824865, 2020). "The therapies using various antibodies or kinase inhibitors inhibit the CCL2/CCR2-, CXCL12/CXCR4-t, or CSF-1/CSF-1R-dependent monocyte/macrophage recruitment into the tumor." (PMID 33352942, 2020). "QRHX also reduces the expression of CXCL12/CXCR4 and the phosphorylation of JAK2/STAT3 in tumor tissues." (PMID 33224886, 2020). "CXCL12/CXCR4 axis has been described to play a pivotal role in CSCs maintenance, to guide tumor cell dissemination, and to foster chemoresistance." (PMID 33123122, 2020). "Migration of cancer cells is directly dependent on the interactions between cell surface molecules on the tumor cells, like CXCR4, and the release of chemokines, like CXCL12, by tissues that are targets for metastases." (PMID 31802362, 2020). "MSCs also secrete SDF-1/CXCL12, and communication between CSCs and MSCs through SDF-1/CXCL12 leads to tumor progression through different ways, including CSs survival, tumor growth, metastasis and angiogenesis processes." (PMID 33059744, 2020).